TP73 (tumor protein p73)
Diseases named in the same sentence as TP73 in open-access papers (continued):
Sharing a sentence is not in itself a finding about the gene and the disease.
glioma (continued). "Transcriptional and post‐transcriptional regulation of TP73 might play a critical role in exerting dysfunctions in glioma." (PMID 34121368, 2021). "It was suggested that the predominant cause for the abnormal functions of TP73 in glioma might not the alteration of genome sequence." (PMID 34121368, 2021). "Additionally, we suspect that chromosome 1p/19q codeletion may also play a critical role in aberrant TP73 expression of WHO II/III glioma." (PMID 34121368, 2021). "The expression of TP73 in IDH‐wildtype subtype was significantly higher than that in IDH‐mutant subtype in TCGA_LGG, CGGA_325 and CGGA_693 datasets of WHO grade II/III glioma (p < 0.0001; p = 0.0029; p < 0.0001, respectively)." (PMID 34121368, 2021). "Based on IDH mutation status classification of WHO grade II/III glioma, remarkable differences of TP73 expression between IDH‐mutant subtype and IDH‐wildtype subtype were also observed in WHO II/III glioma." (PMID 34121368, 2021). "But the mechanisms of the TP73 gene aberrance and the manifestation of significant correlation with survival outcome in WHO grade II/III glioma are still poorly understood." (PMID 34121368, 2021). "In our study, integrated with TCGA and CGGA databases, we in‐depth analyzed the correlation between the level of TP73 gene mRNA expression, DNA methylation and the clinical outcomes of WHO grade II/III glioma." (PMID 34121368, 2021). "Our work showed the significant potential of TP73 gene as a molecular characteristic for evaluating the malignancy and survival outcome of WHO grade II/III glioma." (PMID 34121368, 2021). "Our work showed the significant potential of TP73 gene as a molecular characteristic for evaluating the malignancy and survival outcome of WHO grade II/III glioma, which also provided a basis for later research on TP73 gene as a molecular target for glioma targeted therapy." (PMID 34121368, 2021). "The present study confirms these data and extends them by reporting increase in transcript levels of the P1-generated Tp73 transcripts, namely TAp73, ΔEx2p73 and ΔEx2-3p73, (but not ΔN’p73) in a cohort of low-grade adult gliomas." (PMID 17047653, 2006). "Moreover, ROC curves indicated that TP73 expression could predict the OS of 1‐year, 2‐year and 3‐years with considerable predictability in different cohorts of WHO grade II/III glioma." (PMID 34121368, 2021).
bladder cancer (5 papers, 2004 to 2024). "By multivariate analysis before treatment, an allelic imbalance of TP73 was the most useful independent predictive factor in predicting cause-specific survival in bladder cancer patients treated by CRT (P=0.0002, Risk ratio: 3382)." (PMID 15292937, 2004). "One potential mechanism could be that the mutated segments cover specific bladder cancer-related pathogenic genes, such as TP73, KMT2C, and FOXA2, or affect some tumor suppressor genes." (PMID 39349436, 2024). "However, low TP73 expression was observed in bladder cancer and head and neck squamous cell carcinoma, compared to corresponding normal tissues." (PMID 31332036, 2019).
liver cancer (5 papers, 2016 to 2024). An epithelial or non-epithelial malignant neoplasm that arises from the liver. "Illustrates this process, highlighting PSMA and TP73 as pivotal biomarkers in liver cancer at the F1 level." (PMID 39764438, 2024).
meningioma (5 papers, 2015 to 2023). A generally slow growing tumor attached to the dura mater. "Alterations in chromosome 1 were frequently found in meningiomas and include mutations in TP73, CDKN2C, RAD54, EPB41, GADD45A, and ALPL." (PMID 38137885, 2023). "TP73 inactivation by hypermethylation has been investigated as a possible risk factor for malignant meningiomas." (PMID 38137885, 2023). "As mentioned, loss of H3K27me3 modifications has been associated with meningioma recurrence in retrospective clinical studies, and hypermethylation of TIMP3, CDKN2A, and TP73 has been correlated with meningioma grade." (PMID 38001599, 2023). "TP73 is suggested as potential biomarker for higher grade meningiomas, because 70–80% of high-grade tumors have TP73 promotor hypermethylation." (PMID 34385566, 2021). "In addition, hypermethylation of TIMP3, Cyclin-Dependent Kinase Inhibitor 2A (CDKN2A), and TP73 has been correlated with meningioma grade." (PMID 38001599, 2023). "In contrast, although mutation of the TP73 gene has not been found, methylation-mediated inactivation of TP73 has been recurrently reported as frequent in meningiomas." (PMID 25965831, 2015).
head and neck squamous cell carcinoma (4 papers, 2011 to 2020). A squamous cell carcinoma that arises from any of the following anatomic sites: lip and oral cavity, nasal cavity, paranasal sinuses, pharynx, larynx, and salivary glands. "TP73 is considered to be associated with head and neck squamous cell carcinoma." (PMID 33166290, 2020).
squamous cell carcinoma (4 papers, 2016 to 2024). A carcinoma arising from squamous epithelial cells. "We also found that the CC homozygous genotype of the rs2273953 in the TP73 gene had significant importance in chemotherapy and survival time of squamous cell carcinoma." (PMID 27246533, 2016). "It is therefore likely that TP73 isoform regulation in cancer cells is less stringent than in normal cells, and further studies will be necessary to elucidate TP73 isoform regulation and the clinicopathologic characteristics of ΔTAp73 and TAp73 in squamous cell carcinomas and other tumour types." (PMID 39622910, 2024). "In squamous cell carcinoma (SCC), as the rs2228000, rs2228001 (XPC), rs2273953 (TP73), rs2279744 (MDM2), rs2299939 (PTEN) and rs8178085, rs12334811 (DNA-PKcs) affected the sensitivity to chemotherapy, so did the rs8178085, rs12334811 to radiotherapy." (PMID 27246533, 2016).
colon tumor (3 papers, 2019 to 2023). "Cytolytic-high colon tumors on the other hand, were characterized by recurrent deletions at loci 1p35.3 (PIK3CD, TP73, miR34a), 6p25.3 (FOXC1), and 21q11.1 (Let-7c), and amplifications at loci 8q24.21 (MYC) and 20q13.12 (MMP9)." (PMID 31429779, 2019). "Furthermore, we have identified significant upregulation of key transcription factor interactions in colon cancer patients, including the apoptotic regulation facilitated by E2F1, MYC, and MYCN, as well as activation of the BCL-2 protein family facilitated by TP73." (PMID 37398471, 2023).
laryngeal carcinoma (3 papers, 2019 to 2022). Carcinoma that arises from the laryngeal epithelium. "High expression of YAP1, TEAD4, and TP73 was significantly associated with high grade, advanced stage, supraglottic location of tumors, nodal metastases, and recurrence of human laryngeal cancer." (PMID 36479120, 2022). "On the contrary, upregulated TP73 was found significantly associated with worse OS and DFS outcomes in laryngeal cancer." (PMID 35756491, 2022).
lung squamous cell carcinoma (3 papers, 2016 to 2022). "The results showed that the SNPs in XPC (rs2228000 and rs2228001), TP73 (rs2273953), MDM2 (rs2279744), PTEN (rs2299939) and DNA-PKcs (rs8178085 and rs12334811) genes significantly affected the sensitivity of lung squamous cell carcinoma to chemotherapy." (PMID 27246533, 2016).
skin cutaneous melanoma (3 papers, 2018 to 2022). "However, TP73 mRNA was statistically decreased in a number of malignancies, including pancreatic adenocarcinoma (PAAD), skin cutaneous melanoma (SKCM), and testicular germ cell tumors (TGCT)." (PMID 35756491, 2022).
Alzheimer disease (2 papers, 2013 to 2016). A progressive, neurodegenerative disease characterized by loss of function and death of nerve cells in several areas of the brain leading to loss of cognitive function such as memory and language. "Furthermore, TP73 has been found to be critical for normal neuronal development and survival, making it a potential candidate gene for susceptibility to Alzheimer's disease (AD)." (PMID 27536236, 2016).
amyotrophic lateral sclerosis (2 papers, 2022 to 2023). Amyotrophic lateral sclerosis (ALS) is a neurodegenerative disease characterized by progressive muscular paralysis reflecting degeneration of motor neurons in the primary motor cortex, corticospinal tracts, brainstem and spinal cord. "TP73 was recently identified as a novel causative gene for amyotrophic lateral sclerosis (ALS)." (PMID 36845660, 2023).
asthma (2 papers, 2020 to 2022). "We integrated published datasets to identify epithelium-specific transcription factors associated with H3K27ac in asthma (TP73) and identify initial relationships between asthma-associated changes in H3K27ac and transcriptional profiles." (PMID 33362848, 2020). "The highest difference in Delta β (0.148) corresponds to the cg18873878 observed within the TSS200 region of the TP73 gene being hypermethylated in RW-RSV children in comparison with those with asthma." (PMID 35619695, 2022). "We focused on Epithelium-dominant TFs and found those encompassed by BEC-SEs have been previously implicated in lung development (FOXA1) and asthma, nasal polyposis, and mucociliary development (TP63, TP73)." (PMID 33362848, 2020). "We found that a number of TFs were encompassed by BEC-SEs including TP63, a well-defined marker of basal cells, and TP73, a key player in mucociliary development and observed enrichment for FOXI1 sites in asthma DERs, a TF shown to characterize the recently identified ionocytes." (PMID 33362848, 2020).
astrocytoma (2 papers, 2011 to 2015). "Overall, our results support the idea that G. verrucosa extract and purified DhL can inhibit the growth of the tumor lines, particularly of D384 astrocytoma cells, by activating cell cycle arrest and apoptosis through a TP73-dependent mechanism." (PMID 26309132, 2015).
B-cell chronic lymphocytic leukemia (2 papers, 2011 to 2022). "Overexpression of TP73 is a common feature of B-cell chronic lymphocytic leukemia and may be involved in tumorigenesis by altering the ratio between oncogenic and anticancer gene variants of TP73." (PMID 35756491, 2022).
breast tumors (2 papers, 2018 to 2025). "TP73 mRNA expression was significantly higher in breast tumour tissue compared to normal breast tissue (p < 0.0001)." (PMID 41153767, 2025). "Analyses of breast tumors from patients and cell lines derived from breast tumors show a higher expression of TP73 compared with normal tissues and cells." (PMID 30510575, 2018).
endometriosis (2 papers, 2018 to 2023). The growth of functional endometrial tissue in anatomic sites outside the uterine body.
Infertility (2 papers, 2015 to 2018). "Another study with women submitted to in vitro fertilization (IVF) treatment showed an association of one single nucleotide polymorphism–SNP (rs4648551, A>G) on the TP73 gene with infertility, exhibiting a clear enrichment of the G allele in older infertile women (>35 years)." (PMID 25794170, 2015).
Multiple Myeloma (2 papers, 2011 to 2017). "Moreover, TP73 is rarely mutated but frequently silenced by CpG methylation in hematological malignancies and in multiple myeloma (MM)." (PMID 29295500, 2017).
Obesity (2 papers, 2021 to 2024). Accumulation of substantial excess body fat. "TP73, PIK3R2, SLC9A3R1, KRT5, KRT14 and TFAP2C are novel biomarkers for pathogenesis of obesity associated type 2 diabetes mellitus." (PMID 33902539, 2021). "The hub genes CEBPD, TP73, ESR2, TAB1, MAP 3K5, FN1, UBD, RUNX1, PIK3R2 and TNF, which might play an essential role in obesity associated type 2 diabetes mellitus was further screened." (PMID 33902539, 2021). "These hub genes were associated with progression of obesity associated type 2 diabetes mellitus and first five (CEBPD, TP73, ESR2, TAB1 and MAP 3K5) of them might be linked with targeted therapy." (PMID 33902539, 2021).
pancreatic cancer (2 papers, 2019 to 2023). "In human pancreatic cancer cells, TP73 monoallelic expression was also observed and correlated with patient outcome." (PMID 37568607, 2023).
thymoma (2 papers, 2017 to 2022). A neoplasm arising from the epithelial cells of the thymus. "Additionally, overexpression of TP63 and TP73 was frequently observed in thymomas." (PMID 28258440, 2017). "Thus TP63/TP73 may be promising new targets for treating thymomas." (PMID 28258440, 2017).
thyroid cancer (2 papers, 2022).
alopecia (1 paper, 2015). Hair loss usually from the scalp. "Although the cellular functions of miR-602, RASSF1A and TP73 have not been investigated in DP cells, the data of the present study suggested that the interaction between miR-602 and the two genes may be functionally involved in ROS-induced cellular stress and even alopecia-associated mechanisms." (PMID 25955790, 2015).
autism (1 paper, 2016). Persistent deficits in social interaction and communication and interaction as well as a markedly restricted repertoire of activity and interest as well as repetitive patterns of behavior. "GABPA was recently found to bind human-specific binding sites and regulate gene expression of at least four genes (ALDOA, HSPA8, TP73, and TMBIM6) that have been associated with cognitive diseases such as autism, AZ, PD and other brain disorders." (PMID 27014338, 2016).
autoimmune disease (1 paper, 2025). A disorder resulting from loss of function or tissue destruction of an organ or multiple organs, arising from humoral or cellular immune responses of the individual to their own tissue constituents. "TP73 has been shown to regulate T helper differentiation-related genes, which results in variation in autoimmune disease susceptibility in mice." (PMID 40483267, 2025).
B-cell lymphomas (1 paper, 2011). "In our series, TP73, one of the potential 1p36 candidate tumor suppressor genes in B-cell lymphomas, was deleted in 35 out of 39 cases with unbalanced non-telomeric rearrangements." (PMID 22039459, 2011).
colorectal tumor (1 paper, 2019). "Moreover, increased TP73 mRNA expression was observed in colorectal tumor tissues compared to corresponding normal tissues." (PMID 31090204, 2019).
endometrial cancer (1 paper, 2022). Primary or metastatic malignant neoplasm involving the endometrium (mucous membrane that lines the endometrial cavity). "We also identified the prognostically important genes related to apoptosis, such as those encoding KIAA1324 and TP73, in endometrial cancer." (PMID 36358786, 2022). "Among them, we identified four genes (SFN, CDKN1A, GADD45G, and TP73) whose expression was positively correlated with endometrial cancer from TCGA data." (PMID 36358786, 2022). "In conclusion, SETD8 and TP73 are important genes for the carcinogenesis and progression of endometrial cancer and represent new therapeutic targets that need to be evaluated in the future." (PMID 36358786, 2022). "KIAA1324 and TP73 were two of the top five genes related to apoptosis, suggesting their prognostic importance for endometrial cancer prognosis." (PMID 36358786, 2022). "Expression levels of TP73 and KIAA1324 were significantly upregulated in siSETD8-transfected and UNC0379-treated endometrial cancer cells." (PMID 36358786, 2022). "Our immunoblotting and immunocytochemistry data suggest that SETD8 knockdown with siRNA or a SETD8-selective inhibitor in endometrial cancer cell lines led to a decrease in H4K20 methylation, an increase in TP73 expression, and ultimately, apoptosis." (PMID 36358786, 2022). "Second, although we identified new prognostic genes such as KIAA1324 and TP73, it is possible that other genes regulated by H4K20 methylation are involved in endometrial cancer development." (PMID 36358786, 2022). "H4K20me1 ChIP-qPCR on SETD8-knockdown endometrial cancer cells further confirmed that the expression of KIAA1324 and TP73 was indeed regulated by SETD8 via H4K20 methylation." (PMID 36358786, 2022). "To confirm whether SETD8 regulates KIAA1324 and TP73, we performed quantitative real-time qPCR, immunoblotting, and immunocytochemistry with siSETD8-transfected and UNC0379-treated endometrial cancer cells." (PMID 36358786, 2022). "In contrast to some reports associated with KIAA1324 expression, there are no reports on the correlation between TP73 expression and prognosis of endometrial cancer patients." (PMID 36358786, 2022).
ependymoma (1 paper, 2009). A WHO grade II, slow growing tumor of children and young adults, usually located intraventricularly. "The tumors suppressor genes RASSF1, CDKN2A, CDKN2B, p14ARF and TP73, as well as other genes potentially involved in the tumorigenesis of ependymomas, such as CASP1, MGMT, TIMP3 and THBS1 are epigenetically silenced by aberrant promoter methylation in subsets of ependymomas." (PMID 19333441, 2009).
epithelial dysplasia (1 paper, 2022). "In addition, methylation of KLLN, CHFR, TP73, GSTP1, and CASP8 may be related to precancerous processes, such as epithelial hyperplasia and epithelial dysplasia." (PMID 35681626, 2022).